RN7SL106P (RNA, 7SL, cytoplasmic 106, pseudogene)
Gene: Miscellaneous RNA gene on chromosome 15 (23,165,897 to 23,166,186, forward strand). Ensembl gene ENSG00000273981.
Homologues: Orthologues: pig Metazoa_SRP (54% identical), macaque Metazoa_SRP (48% identical). Paralogues in human: Metazoa_SRP (100% identical), RN7SL238P (100% identical), RN7SL536P (99% identical), RN7SL545P (99% identical), RN7SL759P (99% identical), RN7SL196P (88% identical), RN7SL286P (88% identical), RN7SL539P (88% identical), RN7SL796P (88% identical), RN7SL214P (79% identical), RN7SL736P (79% identical), RN7SL209P (78% identical), and 700 more.